SYT5 (synaptotagmin 5)
Description:
May be involved in Ca(2+)-dependent exocytosis of secretory vesicles through Ca(2+) and phospholipid binding to the C2 domain or may serve as Ca(2+) sensors in the process of vesicular trafficking and exocytosis. Regulates the Ca(2+)-dependent secretion of norepinephrine in PC12 cells. Required for export from the endocytic recycling compartment to the cell surface (By similarity).
Tractability: Antibody: UniProt predicts a signal peptide or a membrane-spanning region; its Gene Ontology location is reachable by antibodies, with medium confidence. PROTAC: ubiquitination databases record sites on it; its protein half-life has been measured.
Gene: Protein-coding gene on chromosome 19 (55,171,196 to 55,180,314, reverse strand). Ensembl gene ENSG00000129990.
Subcellular location: Cytoplasmic vesicle, secretory vesicle, synaptic vesicle membrane; Recycling endosome membrane
Pathways (Reactome):
Metabolism: Regulation of insulin secretion
Gene Ontology:
Molecular function: calcium ion binding; calcium ion sensor activity; calcium-dependent phospholipid binding; SNARE binding; clathrin binding; phosphatidylinositol-4,5-bisphosphate binding; phosphatidylserine binding; protein heterodimerization activity
Biological process: calcium-dependent activation of synaptic vesicle fusion; chemical synaptic transmission; regulation of calcium ion-dependent exocytosis; regulation of synaptic vesicle exocytosis; vesicle-mediated transport
Cellular component: axon; dense core granule; exocytic vesicle; plasma membrane; synaptic vesicle membrane; membrane; neuron projection; neuronal cell body; neuronal dense core vesicle membrane; perinuclear region of cytoplasm; proximal neuron projection; recycling endosome membrane
Genetic constraint (gnomAD): Loss-of-function variants: 32 observed, 36.79 expected, observed/expected ratio (o/e) 0.87, 90% interval 0.66 to 1.17. The upper end of that interval is the gene's LOEUF score, 1.17, which puts it in group 5 of 6, group 1 being the genes least tolerant of losing a copy. Missense variants: 512 observed, 477.56 expected, observed/expected ratio (o/e) 1.07, 90% interval 1 to 1.15. Synonymous variants: 231 observed, 202.62 expected, observed/expected ratio (o/e) 1.14, 90% interval 1.02 to 1.27.
Homologues: Orthologues: chimpanzee SYT5 (100% identical), macaque SYT5 (98% identical), pig SYT5 (96% identical), guinea pig SYT5 (91% identical), mouse Syt5 (91% identical), rat Syt5 (91% identical), dog SYT5 (81% identical), tropical clawed frog syt5 (66% identical). Paralogues in human: SYT1 (60% identical), SYT2 (59% identical), SYT6 (41% identical), SYT8 (39% identical), SYT3 (39% identical), SYT9 (37% identical), SYT10 (36% identical), SYT7 (35% identical), SYT11 (34% identical), SYT4 (32% identical), SYT17 (30% identical), DOC2A (29% identical), and 19 more.
Diseases named in the same sentence as SYT5 in open-access papers:
SYT5 is named in the same sentence as 14 diseases in open-access papers, as found by Europe PMC text mining. Sharing a sentence is not in itself a finding about the gene and the disease. The quoted sentences say what the papers report.
Arthritis (1 paper, 2024). Inflammation of a joint. "Our observations show that Mg supplementation increases the levels of Syt5, and while the precise mechanism of action of this gene in arthritis and cancer remains unknown, increasing dietary Mg may be an option worth considering in future trials in RA and cancer." (PMID 39683640, 2024).
glioblastoma (1 paper, 2024). The most malignant astrocytic tumor (WHO grade IV). "Little is known about the exocytosis regulator gene Syt5, but its expression is associated with increased survival in renal carcinoma and glioblastomas." (PMID 39683640, 2024).
glioma (1 paper, 2020). A benign or malignant brain and spinal cord tumor that arises from glial cells (astrocytes, oligodendrocytes, ependymal cells). "We identified two gene signatures composed of SLC32A1/MSR1 and SYT5/C5AR1 gene combinations whose expression alone strongly correlated with this subgroup of IDH-WT gliomas." (PMID 33059718, 2020). "In contrast, the SLC32A1 and SYT5 genes were underexpressed in the OT cluster and in higher-grade gliomas." (PMID 33059718, 2020). "Using the first CGGA dataset, 14 samples were classified as NL gliomas with both SLC32A1/MSR1 and C5AR1/SYT5 gene signatures vs 263 OT samples." (PMID 33059718, 2020). "A machine learning-based approach identified C5AR1/SYT5 and MSR1/SLC32A1 signatures which were able to discriminate NL IDH-WT gliomas with high sensitivity and specificity in various glioma expression datasets." (PMID 33059718, 2020).
neuroblastoma (1 paper, 2021). Neuroblastoma (NB) is the most common solid, extracranial childhood tumor. "In order to further confirm both, expression of Syt5 in SiMa neuroblastoma cells and interactions of α-HPy and α-CJe with Syt5 in these cells, a-gene specific knockdown of the Syt5 mRNA was performed by transfecting these cells with a commercial Syt5 shRNA expression vector." (PMID 32860155, 2021).
schizophrenia (1 paper, 2021). A major psychotic disorder characterized by abnormalities in the perception or expression of reality. "Hints for a role of Syt5 in schizophrenia pathology come from the fact that in rats treated with neuroleptic drugs, expression of Syt5 is reduced in the frontal cortex." (PMID 32860155, 2021). "For both α-HPy and α-CJe, several established schizophrenia candidate proteins with cross-reactivity to either of these antibodies could be identified including Syt5, Slc17a7, Stmn4, and Ncan." (PMID 32860155, 2021). "By this we could identify and confirm among others synaptotagmin 5 (Syt5), a synaptic calcium sensor, and a protein with potential relevance for schizophrenia pathology as a cellular interaction partner for α-HPy." (PMID 32860155, 2021).
neurodevelopmental disorder (1 paper, 2021). A behavioral and cognitive disorder with onset during the developmental period that involves impaired or aberrant development of intellectual, motor, or social functions. "In conclusion, the present study supports the view that prenatal maternal antibacterial immune responses towards HPy and by this to Syt5 are able to cause functional changes, which in the end might contribute also to neurodevelopmental disorders." (PMID 32860155, 2021).
SYT5 also shares sentences with these, for which no sentence is quoted: asthenia (1 paper); brain injury (1); cancer (1); infection (1); Insulin resistance (1); lung carcinoma (1); renal carcinoma (1); type II diabetes (1).